TLR8 (toll like receptor 8)
Diseases named in the same sentence as TLR8 in open-access papers (continued):
Sharing a sentence is not in itself a finding about the gene and the disease.
tumor (continued). "Activation of Toll-like receptor 8 (TLR8) in tumor cells can down-regulate the level of tumor-derived cAMP, block and reverse the aging process, and restore the anti-tumor ability of T cells." (PMID 38415245, 2024). "Tumour-secreted miRNAs (miR-21 and miR29a) have been shown to bind directly to human Toll-like receptor 8, activating a Toll-like receptor-mediated inflammatory response that can result in tumour growth and metastasis." (PMID 37568712, 2023). "Activation of the TLR8 signaling pathway leads to the production of IFN-α and pro-inflammatory cytokines such as TNF-α, IL-1β, IL-6, IL-12, suggesting that TLR8 plays an important role in cellular immunity, anti-tumor, antiviral and anti-infection of the body." (PMID 38104080, 2023). "In GI tumors, both TLR7 and TLR8 agonists in combination with RT showed a significant decrease in tumor growth." (PMID 37112730, 2023). "TLR8 activation using these ligands was shown to block effector T cells from entering senescence by inhibiting tumor-derived endogenous cyclic adenosine monophosphate (cAMP), which is responsible for this conversion." (PMID 37112730, 2023). "Compared to CD8+ cells accumulated in stromal region, TLR8+ cells and PD‐L1+ cells were more accumulated in parenchymal/tumor region." (PMID 38063246, 2023). "The combination of a TLR3 and TLR8 agonist repolarizes TAMs into pro-inflammatory macrophages, reduces tumor growth and increases T cell infiltration into tumors." (PMID 37143666, 2023). "Overall, TLR8 should be investigated as a predictive biomarker for tumor immune infiltration and immunotherapy; however, the mechanism of action of TLR8 in immunotherapy needs to be further explored." (PMID 38063246, 2023). "Recent studies show that TLR8 stimulation in humans reverses Tregs’ immunosuppressive function and enhances their anti-tumor function by inhibiting glycolysis and glucose uptake." (PMID 35309296, 2022). "Anti-tumor immune responses were enhanced with TLR8-mediated signaling by the inhibition of suppressive activity of Tregs." (PMID 35812393, 2022). "At the same time, the activation of TLR8 can also induce the apoptosis of MDSCs that inhibit immune response, leading to the activation and enhancement of tumor immune response." (PMID 36476317, 2022). "Lung tumor cell-derived exosomes can transfer miR-21/29a to activate TLR7 and TLR8 in immune cells, which were promoted to tumor development and metastasis." (PMID 35711455, 2022). "The Croce group first identified tumor-secreted miR-21 and miR-29a as ligands that bind to TLR7 and TLR8 of immune cells, triggering a pro-metastatic inflammatory response and changing the microenvironment of tumor growth or metastasis." (PMID 35637969, 2022). "TLR8 signaling selectively inhibits glucose uptake and glycolysis in Treg cells, thereby reversing Treg suppression and enhancing in vivo anti-tumor immunity in a melanoma adoptive T cell transfer therapy model." (PMID 36365103, 2022). "R848, which normally activates both TLR7 and TLR8 on DCs, macrophages and neutrophils, activates the CD56brightCD16− NK cell subpopulation only via TLR8, highlighting the potential role of TLR8-targeted infiltrating TME-NK cells as a novel tumor immunotherapy." (PMID 36365103, 2022). "The activation of mDC via TLR-8 by RSQ can effectively promote CD8+ T cell tumor recognition and polarize CD4+ T cells towards Th1 immune responses." (PMID 36297510, 2022). "In KIRC, the results suggested that the mRNA levels of TLR1, TLR2, TLR3, TLR4, TLR7, and TLR8 were elevated in tumour tissues compared with normal kidney tissues." (PMID 34531911, 2021). "TLR7/TLR8 activation via TLR7/TLR8 agonist R848 induces M-MDSC differentiation into anti-tumor M1-type macrophages, whereas TLR1/TLR2 activation facilitates the M-MDSC transformation into suppressive M2-type macrophages." (PMID 34336860, 2021).
tumor (continued). "In cancer, miR-21 and miR-29a from tumor-derived EVs/Exs bind to Toll-like receptors, such as human TLR8, and lead to TLR-mediated NFκB activation and secretion of pro-metastatic inflammatory cytokines, which in turn promotes tumor growth and metastasis." (PMID 33808520, 2021). "Muller found that human tumor cells can secrete miR-21 and miR-29a, which bind to TLR8 in immune cells and activate TLR8, leading to activation of NF-κB and secretion of pro-inflammatory cytokines." (PMID 34516355, 2021). "Recent research demonstrated that tumor-derived T-reg cells exhibit an accelerated glucose uptake, competing with effector T cells for glucose through TLR8 signaling, leading to MAPK activation, which induces T cell senescence." (PMID 34447383, 2021). "TLR8-mediated signaling in tumor cells reversed immune suppression in the tumor microenvironment via blocking cAMP production." (PMID 34124272, 2021). "Of interest, activation of TLR8 signaling in tumor cells reverses this event resulting in enhanced anti-tumor immunity." (PMID 34447383, 2021). "Activated TLR8 pathway remarkably reshapes the tumor immune microenvironment by decreasing infiltrating myeloid-derived suppressor cells (MDSCs), regulatory T cells (Tregs), and immunosuppressive markers, such as CTLA-4." (PMID 33386920, 2021). "Prior study has revealed that TLR8 can prevent T-cell senescence and further enhance tumor immunosuppressive function." (PMID 32228580, 2020). "TLR8 agonists have already been shown to reverse the T cell tumor-induced senescence in mouse models of cancer." (PMID 33008037, 2020). "It has been demonstrated that human TLR8 signaling can reverse the suppressive functions of naturally occurring Treg cells and tumor-derived CD4+, CD8+, and γδ Treg cells, which resulted in enhanced anti-tumor immunity." (PMID 33102225, 2020). "To address this challenge, we applied high doses of DN052 in syngeneic mouse tumor models to offset the reduced receptor activity of TLR8 in mice." (PMID 35006413, 2020). "First, from the efficacy perspective, TLR8 has been shown to be necessary and sufficient to reverse the immune suppressive function of Treg cells leading to strong tumor inhibition." (PMID 35006413, 2020). "Novel anti-HER2 antibody conjugates include SBT6050, which has been designed to carry the Toll-like receptor 8 (TLR8) agonist payload specifically to the tumor microenvironment of HER2 overexpressing cancers." (PMID 31101074, 2019). "Recent studies implicate metabolic regulation of tumor cells by Toll-like receptor 8 (TLR8) signaling." (PMID 29973238, 2018). "We have identified that activation of human Toll-like receptor 8 (TLR8) signaling in Treg cells and multiple types of tumor cells can prevent effector T cell senescence and reverse the suppressive activity mediated by both Treg and senescent T cells." (PMID 29339767, 2018). "Conversely, in A549 cells, TLR7 or TLR8 agonists led to increased tumor cell survival, chemoresistance, and increased anti-apoptotic protein expression, as well as appear to increase MDSCs and reduce CD8+ T cells in mice, promoting tumor growth." (PMID 29190881, 2017). "In the current study, we show that DC matured in the presence of a combination of IFNγ and ligands for TLR3 (poly I:C), TLR4 (LPS), and TLR8 (R848) display features crucial for triggering efficient T cell-mediated anti-tumor responses." (PMID 28601925, 2017). "Positive staining for TLR4 and TLR8 was observed in macrophages around the periphery of the tumors, but sparse staining was observed within the tumor itself." (PMID 29190881, 2017). "This novel exosomic miR-21/ TLR8/NF-кB/exosomic miR-155/TERF1 axis suggests that exosomes within the tumor microenvironment are important molecular targets to restore drug sensitivity." (PMID 28231804, 2017).
tumor (continued). "While TLR8-inducible mediators, including IL-12 and IL-18, act cooperatively on NK cells, additional signals including tumor-expressed NKG2D ligands, and FcγRIII activation via ADCC, intensify the response." (PMID 26928328, 2016). "Enhanced NK cell-mediated lysis of tumor cells should complement other TLR8 responses, facilitating the development of a durable, tumor-specific, adaptive immune response." (PMID 26928328, 2016). "Conversely, different studies have described pro-tumoral effects when TLR pathways were activated in tumor cells, including TLR8 6, arguing against the systemic or local use of TLR8 synthetic agonist in cancer immunotherapy." (PMID 25866635, 2015). "At a concentration of 100 μmol/l of 5-FU relative cell viability of TLR7+ and TLR8+ PANC1 tumor cells was less reduced when compared with empty vector PANC1 tumor cells (62 and 73% vs. 58% for empty vector cells; P<0.05 and P<0.0001)." (PMID 26134824, 2015). "We then focused our study on the effect of a direct CTL stimulation through TLR8 engagement on tumor antigen-specific CTL function." (PMID 25866635, 2015). "We found that activation of TLR8 signaling in tumor cells can block tumor-induced conversion of naïve and tumor-specific T cells into senescent cells and reverse senescent T-cell-mediated suppression, resulting in enhanced anti-tumor immunity in vivo." (PMID 25231413, 2014). "Our previous and current studies strongly indicate the advantages of the development of TLR8-targeted immunity for anti-tumor immunotherapy." (PMID 25231413, 2014). "In our efforts to explore the strategies for reversing tumor suppressive microenvironments, we further showed that TLR8 signaling can reverse tumor-induced T-cell senescence by blocking cAMP production in tumor cells." (PMID 25231413, 2014). "Third, our current studies further show that human TLR8 signaling can also directly target multiple types of tumor cells and prevent their ability to induce T-cell senescence." (PMID 25231413, 2014). "The mechanism regulated by TLR8 signaling appears to involve modulation of the levels of the endogenous secondary messenger cAMP in tumor cells, strongly implicating the involvement of metabolic regulation mediated by TLR8 signaling." (PMID 25231413, 2014). "Most importantly, our results clearly showed that TLR8 signaling can prevent the cAMP production by tumor cells and block tumor-induced conversion of naïve and tumor-specific T cells into senescent cells, resulting in enhanced anti-tumor immunity in vivo." (PMID 25231413, 2014). "Collectively, our studies clearly demonstrate that TLR8 signaling can reverse tumor-induced T-cell senescence through the down-regulation of endogenous cAMP levels in tumor cells." (PMID 25231413, 2014). "Collectively, our studies clearly indicate that human TLR8 signaling can reverse the suppressive effects mediated by tumor microenvironments and switch it into an effector microenvironment, by targeting different types of cells at different levels." (PMID 25231413, 2014). "MCF7, PC3, and M628 tumor cells were transfected with lenti-shRNAs specific for TLR8, MyD88, or IRAK4 molecules, or control lenti-shRNA, and then their ability to induce T-cell senescence in the presence of Poly-G3 was determined." (PMID 25231413, 2014). "Our future studies will focus on providing a better understanding of the molecular mechanisms and unique signaling pathways involved in the effects of how TLR8 signaling regulates tumor and Treg cell functions." (PMID 25231413, 2014). "We have demonstrated that human TLR8 signaling directly reversed the suppressive functions of naturally occurring CD4+ CD25+ Treg cells as well as tumor-derived CD4+, CD8+, and γδ Treg cells." (PMID 25231413, 2014). "TLR7 and TLR8 agonists reverse TAMs from M2 to M1, reducing radiation resistance and tumor growth." (PMID 40948759, 2025).
tumor (continued). "TLR8 may impact the tumor microenvironment by activating immune responses, thereby influencing disease progression and treatment strategies." (PMID 41208992, 2025). "Whereas their ligation in immune cells may enhance anti-tumour activity, TLR7 and TLR8 are also expressed in tumour cells where they mediate a pro-tumour effect." (PMID 40336011, 2025). "Additionally, our group was the first to identify a completely novel function of miRs, as ligands of Toll-like receptor 8 (TLR8) promoting a pro-tumoral inflammatory response within the tumor microenvironment, relevant to multiple types of cancers." (PMID 41227342, 2025). "Additionally, TLR8 signaling can reverse the inhibition of Tregs and tumor cells and prevent T cell senescence." (PMID 38415245, 2024). "Likewise, cAMP inhibitors (7-ddA), or synthetic poly-G3 and natural TLR8 ligands (ssRNA40), can also suppress tumor- and Treg-induced T cell aging by reactivating TLR8 signaling." (PMID 39684260, 2024). "TLR8 signaling plays a pivotal role in immune regulation, particularly through enhancing Treg functionality and reprogramming glucose metabolism to boost anti-tumor immunity." (PMID 39731171, 2024). "cAMP inhibitors also inhibit tumor-induced T-cell senescence by reactivating TLR8 signaling." (PMID 38415245, 2024). "Another method is by activating the TLR8 signaling pathway in Treg and tumor cells." (PMID 38415245, 2024). "Given the potential of TLR8 and TNFSF9 as new targets for cancer immunotherapy, how specific HLA-I genotypes influence their expression in tumor microenvironment and the role of HLA-A02+B62+B44− in treatment outcomes of related drugs targeting TLR8 or TNFSF9 deserve to be further studied." (PMID 37026827, 2023). "Therefore, basic studies on the distribution, expression and signaling mechanism of TLR8 are of great significance for revealing the relevant mechanisms of the body's anti-infection, anti-tumor and anti-allergy." (PMID 38104080, 2023). "These previous studies have emphasized the important role of TLR8 in tumor immune microenvironment." (PMID 38063246, 2023). "In lung cancer, the tumor cell-secreted exosomal miR-21 and miR-29a showed that they could connect to the TLR-8, inducing the activation of the NF-kB that leads to the production of pro-inflammatory cytokines, metastasis, and tumor proliferation." (PMID 37514090, 2023). "TLR8 activated mDC is very suitable for producing an acquired immune response against tumor cells." (PMID 36476317, 2022). "TLR8 signaling could reverse the suppressive functions of tumor-derived CD4+ T cells, CD8+ T cells and γδ regulatory T (Treg) cells resulting in enhanced anti-tumor immunity." (PMID 35413927, 2022). "Moreover, the combination of cetuximab with small synthetic compounds able to trigger both TLR7 and TLR8 in a dose dependent manner induced tumor growth inhibition and increased NK cell-mediated ADCC in a lung murine model." (PMID 36672572, 2022). "TLR8 can reverse the immunosuppressive function of Treg cells and has a strong anti-tumor effect." (PMID 36476317, 2022). "Therefore, reversing Treg and MDSC-mediated immunosuppression by activating TLR8 can trigger a strong immune response and produce a strong anti-tumor effect." (PMID 36476317, 2022). "TLR8 signaling reversed tumor-induced T-cell senescence by blocking cAMP production in tumor cells." (PMID 35884895, 2022). "In particular, enhancing tumor cell killing through ADCC may be an important therapeutic opportunity for TLR8 specific agonists." (PMID 36476317, 2022). "The effectd of TLR8-mediated signaling was also evaluated in in vivo tumor models." (PMID 35812393, 2022). "Additional anti-cancer mechanisms may include inhibiting Treg function by binding to TLR-8 on Treg and preventing tumor-induced T cell senescence by blocking the release of cyclic adenosine monophosphate from melanoma cells." (PMID 36297510, 2022).
tumor (continued). "Our studies have raised the question of how EGFR status may be involved in tumor response to TLR8 agonists." (PMID 33452311, 2021). "A study showed that activated TLR8 could prevent cAMP production in tumor cells and block the tumor-induced conversion of naive and tumor-specific T cells into senescent cells, therefore enhancing antitumor immunity in vivo." (PMID 34638609, 2021). "Meanwhile, stimulating TLR8 signal could increase the numbers of tumor-infiltrating M1 monocytes and T cells." (PMID 33386920, 2021). "Additionally, our results clearly demonstrate that TLR8 is functional in mice since the anti-tumor activity of VTX2337 can be observed in 3 different mouse models." (PMID 33452311, 2021). "For TLR8, some studies have shown that miR-21 and miR-29 may secrete exosomes from tumor cells to immune cells, and combine with TLR8 to regulate intracellular signaling pathway." (PMID 34516355, 2021). "In contrast, TLR8 activation of Tregs via TLR8-MyD88-IRAK4 signaling could significantly revert the suppressive function of these cells in a tumor-bearing mouse model." (PMID 34124272, 2021). "Additionally, TLR8 signaling can reverse the suppressive functions of human tumor-derived CD4+ T cells, CD8+ T cells, and γδ T cells, which resulted in enhanced anti-tumor immunity." (PMID 33102225, 2020). "Another compound that indirectly could stimulate the tumor-specific T cell response is the toll-like receptor 8 (TLR8) agonist motolomid, which is known to activate monocytes, DCs and NK cells." (PMID 33425717, 2020). "Furthermore, the activation of Toll-like receptor 8 signaling in tumor cells can enhance antitumor immunity by blocking the induction of senescent T cells and tumor-specific T cells in vitro and in vivo and reversing their inhibitory effect." (PMID 33168037, 2020). "Moreover, TLR8 signaling-mediated reprogramming of glucose metabolism and function in human Treg cells can enhance anti-tumor immunity in vivo in a melanoma model." (PMID 33102225, 2020). "Activation of TLR8 signaling in tumor cells was able to reverse the tumor-induced senescence." (PMID 33008037, 2020). "Therefore, TLR8 is considered a key marker of tumor genesis and is a highly selective candidate to develop anti-proliferative and anti-malignant agents." (PMID 32257888, 2020). "Clinical trials testing combination therapies containing the TLR8-specific agonist motolimod (VTX-2337) for the treatment of various tumor types have been published, and more are currently ongoing or planned (clinicaltrials.gov; NCT03906526, NCT02431559 and NCT04272333)." (PMID 32570952, 2020). "Importantly, TLR8 signaling reverses the suppressive functions of human tumor-derived CD4+ T cells, CD8+ T cells, and γδ T cells." (PMID 33102225, 2020). "A new study showed that TLR8 signaling could mediate the glucose metabolism of tumor-derived Treg cell lines, which resulted in Treg function reversal." (PMID 33102225, 2020). "However, before clinical use, R848 effects on tumor-intrinsic and tumor-extrinsic biology should be further characterized in a model system that expresses TLR8." (PMID 31615993, 2019). "Thus, it will be of interest to determine if, like tumor-released DNA, tumor-released RNA can also facilitate the adjuvant effect of chemotherapy by behaving as an agonist of TLR7 or TLR8 signaling." (PMID 31619293, 2019). "One strategy to turn an immunologically cold tumor hot is to promote activation of antigen presenting cells (APC) by targeting the endosomal TLRs TLR3, TLR7, TLR8, TLR9, or by targeting the ER-associated signalling molecule stimulator of interferon genes (STING)." (PMID 31511088, 2019). "Tumor-secreted microRNAs bind to TLR8 in human immune cells, triggering tumor metastasis." (PMID 30857545, 2019).